KRTAP21-3 (keratin associated protein 21-3)
Description:
In the hair cortex, hair keratin intermediate filaments are embedded in an interfilamentous matrix, consisting of hair keratin-associated proteins (KRTAP), which are essential for the formation of a rigid and resistant hair shaft through their extensive disulfide bond cross-linking with abundant cysteine residues of hair keratins. The matrix proteins include the high-sulfur and high-glycine-tyrosine keratins.
Tractability: No criterion of Open Targets' tractability assessment is met for any kind of drug.
Gene: Protein-coding gene on chromosome 21 (30,718,525 to 30,718,777, reverse strand). Ensembl gene ENSG00000231068.
Pathways (Reactome):
Developmental Biology: Keratinization
Gene Ontology:
Cellular component: cytosol
Genetic constraint (gnomAD): Loss-of-function variants: 0 observed, 0.19 expected, observed/expected ratio (o/e) 0, 90% interval 0 to 1.88. That is too few expected variants to judge how well the gene tolerates losing a copy. Missense variants: 62 observed, 68.93 expected, observed/expected ratio (o/e) 0.9, 90% interval 0.73 to 1.11. Synonymous variants: 21 observed, 23.64 expected, observed/expected ratio (o/e) 0.89, 90% interval 0.63 to 1.28.
Homologues: Orthologues: chimpanzee KRTAP21-3 (97% identical).